NOX4 (NADPH oxidase 4)
Diseases named in the same sentence as NOX4 in open-access papers (continued):
Sharing a sentence is not in itself a finding about the gene and the disease.
Hyperinsulinemia (5 papers, 2012 to 2021). An increased concentration of insulin in the blood. "The mechanistic view behind this impairment is hyperinsulinemia induced Nox4 (NADPH oxidase 4) triggering oxidative stress leading to restrict multipotency and increases adipogenic predictions of diabetic mice." (PMID 32384763, 2020). "T2DM attenuated the capacity of MSC to promote neovascularization in the ischemic hindlimb which was secondary to hyperinsulinemia-induced, Nox4-dependent oxidant stress in db/db MSCs." (PMID 25491476, 2014). "Corresponding in vitro and in vivo experiments showed that hyperinsulinemia-induced Nox4 activity generated the oxidant stress that restricted MSC multipotency and impaired the capacity of MSCs to augment postischemic neovascularization." (PMID 23316315, 2012). "In vitro studies showed that MSC oxidant stress was generated by an hyperinsulinemia-induced increase in Nox4 expression." (PMID 23316315, 2012). "This supposition is based on the pivotal role of hyperinsulinemia-induced, Nox4-derived oxidants in enhancing the adipogenic potential of MSCs established by the in vitro findings of this study." (PMID 23316315, 2012). "The present findings establish that hyperinsulinemia-induced, Nox4-generated oxidant stress is the mechanistic basis for the restricted multipotency and increased adipogenic predilection of db/db MSCs." (PMID 23316315, 2012).
Hyperoxaluria (5 papers, 2012 to 2023). Increased excretion of oxalates in the urine. "In the 14 day treated kidneys, TRPV1 inhibition by Capz or SB significantly reduced Nox4 expression caused by hyperoxaluria." (PMID 34201387, 2021). "Specifically, up-regulated gp91 expression correlated in both the cortex and medulla tissues with CaOx crystal deposition, while Nox4 expression best correlated in the medulla with hyperoxaluria." (PMID 23091645, 2012). "Expression of NADPH oxidase subunits (Nox2 and Nox4) was upregulated in both CaOx-induced NRK-52E cells and rat kidneys in the hyperoxaluria group by Western blotting analysis." (PMID 29849862, 2018).
left ventricular hypertrophy (5 papers, 2015 to 2023). Enlargement of the LEFT VENTRICLE of the heart. "Our study identifies the reactive oxygen species generating enzyme NADPH oxidase-4 (Nox4) as an important regulator of volume overload-induced cardiac remodelling by promoting eccentric left ventricular hypertrophy, an adaptive response to the increased volume." (PMID 31821410, 2021). "Moreover, the importance of Nox4 has been shown in pressure overload-induced left ventricular hypertrophy." (PMID 26557089, 2015).
neuroblastoma (5 papers, 2017 to 2024). Neuroblastoma (NB) is the most common solid, extracranial childhood tumor. "Moreover, expression between MYCN and NOX4 is significantly correlated in MYCN-amplified neuroblastoma samples." (PMID 38493213, 2024). "Using two established tumor cell lines, which are derived from hepatic and neuroblastoma tumors, respectively, we are showing here that in both tumor models Nox4 is expressed in the ER (like the yeast NADPH oxidase), where according to published literature, it produces hydrogen peroxide." (PMID 28620580, 2017). "NOX4-dependent HIFα stabilization is also observed in human neuroblastoma SH-SY5Y cells, in which NOX4 expression is upregulated under hypoxic conditions." (PMID 36768405, 2023). "Indeed, relative luciferase activity was significantly reduced when mouse neuroblastoma (N2a) cells were co-transfected with miR-204-3p and pGL3-NOX4-3′-UTR, but not with the mutant NOX4 luciferase construct." (PMID 36670932, 2022).
periodontitis (5 papers, 2014 to 2026). An acute or chronic inflammatory process that affects the tissues that surround and support the teeth. "In patients suffering from periodontal inflammatory diseases like gingivitis and periodontitis, we demonstrated that NOX4 is upregulated and thus likely responsible for H2O2 generation." (PMID 25374447, 2014). "In particular, SIRT1/NOX4 regulation is considered important in regulating oxidative stress in periodontitis, based on the fact that the interaction between NOX4 and the redox system is important for ROS formation that accelerates periodontitis." (PMID 38790655, 2024). "In addition to the antioxidant effect, we confirmed that HKT has an important inflammation-alleviating effect and osteogenic induction-promoting effect in improving periodontitis through the SIRT1/NOX4 pathway." (PMID 38790655, 2024). "Thus, the present and previous findings suggest that another important source of ROS in the cardiovascular system in patients with periodontitis might be NOX4, besides XO." (PMID 40179080, 2025). "Overall, our results suggest that the XO inhibitor allopurinol might have a protective effect against periodontitis-mediated CVD by blocking the increase of ROS generation mediated by XO and NOX4 in PG-LPS-treated mice." (PMID 40179080, 2025). "In addition, periodontal tissues from clinically healthy patients (I) as well as from patients with the diagnosis of gingivitis (II) and periodontitis (III) were obtained from three different patients for each group and stained immunohistochemically for NOX4, CAT, and SOD." (PMID 25374447, 2014).
acute myeloid leukemia (4 papers, 2019 to 2023). Acute myeloid leukemia (AML) is a group of neoplasms arising from precursor cells committed to the myeloid cell-line differentiation. "Furthermore, suppression of tyrosine kinase FLT3-ITD, p22phox, and NOX4 activity in acute myeloid leukemia (AML) cells leads to reduced cell survivability and reductions in DNA damage and genomic instability according to the research." (PMID 37894287, 2023). "Based on previous studies in acute myeloid leukemia (AML) models, we considered NADPH oxidase (NOX) family members, specifically NOX4 as a potential target in AML." (PMID 35348887, 2022).
asbestosis (4 papers, 2020 to 2024). A lung disorder caused by inhalation of asbestos fibers. "We have shown that subjects with asbestosis have increase transcription of Nox4 compared to normal subjects." (PMID 37044213, 2023). "We have shown that lung macrophages from asbestosis subjects have increased mitochondrial NOX4 in addition to increased mitochondrial ROS production." (PMID 37044213, 2023). "Furthermore, asbestosis subjects have increased localization of NOX4 in mitochondria suggesting that there is rapid translocation into the mitochondria." (PMID 37044213, 2023). "It has been shown that macrophage NOX4 augments mtROS production in asbestosis, suggesting that NOX4 from other cell types, including macrophages, may play a role in enhancing mtROS in fibroblasts." (PMID 32192225, 2020). "Lung macrophages were subjected to NOX4 immunoprecipitation, and immunoblot analysis showed that TIM23 was significantly increased in the lung macrophages from asbestosis subjects." (PMID 37044213, 2023). "TIM23 and NOX4 interaction was found in lung macrophages from human subjects with asbestosis, while it was absent in mice harboring a conditional deletion of NOX4 in lung macrophages." (PMID 37044213, 2023).
Breast invasive carcinoma (4 papers, 2017 to 2022). "In contrast, Nox4 is ranked among the top 1–3% of the most significantly upregulated genes in the stroma of invasive breast carcinomas versus normal breast stroma (median gene rank = 60)." (PMID 35836253, 2022). "However, we found that in breast invasive carcinoma, NOX4 mRNA levels remain unchanged in the different pathological stages." (PMID 33557266, 2021).
colitis (4 papers, 2020 to 2025). Inflammation of the colon. "Nox4−/− mice and wildtype mice showed similar body weight loss and colitis severity during the 20-day disease course." (PMID 33059312, 2020). "Analysis of NRF2 target genes involved in ROS detoxification (Nqo1, Gsta2) and heme/iron metabolism (Hmox1) at the apex of acute murine colitis shows a more nuanced picture with all three genes being differentially affected by Nox4 deficiency." (PMID 33059312, 2020). "Taken together, these data supported that DSC alleviated experimental colitis at least in part through inhibiting Nox4‐mediated NF‐κB and NLRP3 inflammasome activation." (PMID 32945118, 2020). "Taken together, Nrf2 and Nox4 reciprocally regulate the inflammatory response in DSS‐mediated colitis and LPS‐stimulated BMDM, and therefore, it is logical to believe that DSC restores redox homeostasis by regulation of the balance between Nrf2 and Nox4." (PMID 32945118, 2020). "In summary, our study demonstrated that DSC alleviated DSS‐induced colitis by inhibiting Nox4‐mediated NF‐κB and NLRP3 inflammasome activation." (PMID 32945118, 2020). "Ours as well as other previous studies have demonstrated that enhanced Nox4 appears important in various diseases, including colitis." (PMID 32945118, 2020). "To further confirm the role of Nox4 in DSS‐mediated experimental colitis, we delivered lentiviral shRNA to specific Nox4 knockdown in mice." (PMID 32945118, 2020). "In support of this, our results demonstrated that both DSC treatment and genetic Nox4 knockdown interfered with DSS‐induced Nox4 expression and NF‐κB activation in experimental colitis in mice." (PMID 32945118, 2020). "Taken together, the present results demonstrate that DSC attenuates DSS‐mediated colitis via a Nox4‐dependent mechanism." (PMID 32945118, 2020). "We conclude that expression of NOX4 is consistently elevated in human and murine colitis, during fibrogenesis and in strictures." (PMID 33059312, 2020). "Nox1, Nox2 and Nox4 mRNA expression levels were all elevated in experimental colitis." (PMID 32945118, 2020). "Importantly, it is still unclear to what extent Nox4 is important in mediating the process of colitis." (PMID 32945118, 2020). "In the present study, we found that colonic Nox4 expression and ROS and H2O2 generation were significantly increased in DSS‐induced colitis mice, which was accompanied by increased inflammatory mediators and intestinal barrier dysfunction." (PMID 32945118, 2020). "Collectively, our findings indicated a positive correlation of Nox4 levels with colitis and that modulation of Nox4 expression by DSC represented one possible mechanism of its beneficial effects on colitis." (PMID 32945118, 2020). "In wildtype C57BL/6J mice we reported elevated Nox4 expression in acute chemical colitis and observed a spike of Nox4 levels at the onset of infectious colitis (not shown)." (PMID 33059312, 2020). "Thus, in two acute colitis models the absence of Nox4 did not reduce inflammation but amplified tissue damage." (PMID 33059312, 2020).
depression (4 papers, 2021 to 2024). "Upregulation of prooxidant NOX4 and downregulation of antioxidant Nrf2/HO-1 have been implicated in depression-associated oxidative stress and neuroinflammation." (PMID 33621199, 2021). "Of note, therapeutic strategies that target NOX1 and NOX4 downregulation have been envisioned as successful tools for the attenuation of depression and other neurodegenerative diseases." (PMID 37375795, 2023). "NADPH oxidase (NOX) enzymes, particularly NOX4, are present in different brain cell types, and ROS generation via NOX-dependent mechanisms significantly contributes to depression development." (PMID 39769289, 2024). "Memory impairment, a common symptom of depression, may result from the combined effects of increased ER stress and oxidative stress, cholinergic dysfunction, and impaired neuroplasticity, as indicated by the elevation of ER stress markers and NOX4, and reductions in VAChT and β-III-tubulin." (PMID 39769289, 2024). "Together, the present findings prove the neuroprotective/antidepressant actions of meloxicam in CRS-induced depression by ameliorating hippocampal neuroinflammation and pro-oxidant changes, likely by modulating COX-2/NOX1/NOX4/Nrf2 axis." (PMID 37375795, 2023).
diabetic neuropathy (4 papers, 2019 to 2025). A chronic, pathological complication associated with diabetes mellitus, where nerve damages are incurred due to diabetic microvascular injury involving small blood vessels that supply these nerves, resulting in peripheral and/or autonomic nerve dysfunction. "The inhibition of NOX-4 by daidzein decreases the production of reactive oxygen species (ROS), which are key contributors to inflammation and oxidative stress in diabetic neuropathy." (PMID 39166118, 2024). "A study found that hesperidin can protect the oxidative stress response caused by diabetic neuropathy from oxidative damage by upregulating SIRT1 and inhibiting the expression of NOX4, one of the key sources of reactive oxygen species (ROS) production." (PMID 38983771, 2024). "In summary, the findings of study suggests that, Daidzein treatment significantly attenuated diabetic neuropathy by inhibiting oxidative stress via NOX-4 inhibition." (PMID 39166118, 2024). "Therefore, this study was designed to investigate the effects of daidzein on diabetic neuropathy and to examine the involvement of NOX-4 in oxidative neuronal damage under diabetic conditions." (PMID 39166118, 2024). "However, there are no existing reports on the effects of daidzein on diabetic neuropathy through NOX-4 inhibition." (PMID 39166118, 2024).
gallbladder cancer (4 papers, 2020 to 2024). "NOX4 is highly upregulated in gallbladder cancer cells and gallbladder CAFs, which is associated with malignant behaviors and poor prognosis." (PMID 35646942, 2022). "In gallbladder cancer, CAFs can promote VM formation and tumour growth by upregulating NOX4 expression through activation of the IL-6-JAK-STAT3 signalling pathway." (PMID 38459564, 2024).
hearing loss (4 papers, 2022 to 2025). "Transgenic mice overexpressing Nox-4 showed more pronounced vulnerability to noise-induced hearing loss, which was in accordance with the increase in NOX-4 expression in cochlea of noise-exposed mice." (PMID 36719770, 2023). "Note also that the similarities of the protective effect of NOX3 deficiency and p22phox deficiency suggest that there is not a major role of other p22phox-dependent NOX isoforms (i.e. NOX1, NOX2, and NOX4) in the pathophysiology of noise induced hearing loss." (PMID 35273964, 2022).
idiopathic pulmonary arterial hypertension (4 papers, 2012 to 2019). A sporadic form of pulmonary arterial hypertension (PAH) characterized by elevated pulmonary arterial resistance leading to right heart failure. "NOX4 is exclusively upregulated in the pulmonary arterial vessels of mice with chronic exposure to hypoxia and in the vascular lesions of patients with idiopathic pulmonary arterial hypertension (IPAH)." (PMID 28594389, 2017). "In addition to the numerous reports regarding the role of Nox4 in animal models, there is also evidence of significant elevation of Nox4 in lungs of patients with idiopathic pulmonary arterial hypertension (IPAH)." (PMID 31100969, 2019). "Idiopathic pulmonary arterial hypertension (IPAH) patients have 2.5-fold increase in Nox4 expression, which was localized in the vessel media." (PMID 29257052, 2017).
kidney cancer (4 papers, 2017 to 2023). Primary or metastatic malignant neoplasm involving the kidney. "Notably, NOX4 was predominantly expressed in kidney cancers (KIRC and KIRP)." (PMID 28582771, 2017). "The expression of gene CYBA, a critical component of NOX4 NADPH oxidase complex, was significantly increased by apoptosis in kidney cancers (KIRC)." (PMID 28582771, 2017). "However, in malignant kidney tumor cells, TAZ is highly expressed and regulates EMP1 expression, which then induces NADPH oxidase 4 (NOX4) to regulate ferroptosis." (PMID 36090052, 2022).
memory impairment (4 papers, 2020 to 2024). "Memory impairment produced by LPS injection was partially reversed with pharmacological treatment using the inhibitor of NOX4 GKT136901." (PMID 37760032, 2023). "The results showed that electroacupuncture therapy ameliorated spatial learning and memory impairment in cerebral hypoperfusion rats; and electroacupuncture therapy reduces neuronal apoptosis and oxidative stress by activating miR-137/NOX4 axis." (PMID 33986822, 2021). "Taken together, the absence of NOX4 and its pharmacological inhibition improves memory impairment induced by LPS challenge in mice." (PMID 37760032, 2023). "Furthermore, in NOX4 KO animals, injection of LPS did not produce any memory impairment compared with NOX4 KO vehicle mice." (PMID 37760032, 2023).
Muscular dystrophies (4 papers, 2016 to 2025). "Indeed, pathologies that cause a progressive loss of muscle mass, such as muscular dystrophies, are characterized by an over-expression of NOX4, the inhibition of which produces the restoration of muscle-specific stem cells and, consequently, of regenerative potential." (PMID 39846667, 2025). "A recent report established a signaling axis in muscular dystrophy that involves crosstalk between Nox4 and Nox2 contributing to skeletal muscle weakness where the levels of Nox4 can impact the levels of Nox2." (PMID 36436728, 2023). "Muscular dystrophies are inherited disorders and have been associated with the overexpression of NOX2, NOX4, DUOX1, and p47phox." (PMID 27847553, 2016).
peripheral nerve injury (4 papers, 2017 to 2025). Injury to a peripheral nerve. "Nox4 mRNA is present in sensory neurons, and Nox4-derived ROS contribute to pain signalling after peripheral nerve injury." (PMID 31612077, 2019). "NOX4 has previously been connected with neuropathic pain after a peripheral nerve injury." (PMID 40076510, 2025). "Nox4 has been known to contribute to pain signalling after peripheral nerve injury." (PMID 31612077, 2019). "And Nox4 contributes to pain signaling after peripheral nerve injury." (PMID 28674486, 2017).